CHI3L1 (chitinase 3 like 1)
Diseases named in the same sentence as CHI3L1 in open-access papers (continued):
Sharing a sentence is not in itself a finding about the gene and the disease.
osteoarthritis (35 papers, 2005 to 2025). A noninflammatory degenerative joint disease occurring chiefly in older persons, characterized by degeneration of the articular cartilage, hypertrophy of bone at the margins and changes in the synovial membrane. "By binding to CHI3L1(YKL40) and preventing its interaction with other molecules or receptors, this approach aims to mitigate the pathological processes associated with osteoarthritis." (PMID 38543093, 2024). "CHI3L1 can be a potential marker for the severity and progression of osteoarthritis cartilage degeneration." (PMID 39253583, 2024). "CHI3L1(YKL40) has been found to be elevated in the synovial fluid and serum of osteoarthritis patients, suggesting its involvement in the disease process, and the use of CHI3L1(YKL40) as a target for therapy in osteoarthritis is a topic of ongoing research." (PMID 38543093, 2024). "Chi3l1 has been widely demonstrated to be a potential biomarker for the severity of osteoarthritis (OA)." (PMID 39769202, 2024). "Human chitinase-3-like-1 protein, YKL-40 synthesis is related to alteration of cartilage in osteoarthritis and to altered joint mechanical conditions after anterior cruciate transection in dogs." (PMID 34707508, 2021). "In RA, circulating levels of Chitinase 3-Like-1 reflect cartilage degradation and synovial inflammation, and in osteoarthritis this cartilage glycoprotein have been suggested as a potential target for treatment." (PMID 31072030, 2019). "Supporting this concept, recent single-cell analysis of osteoarthritis identified distinct synovial fibroblast subsets with elevated CHI3L1 expression, demonstrating that fibroblast subpopulations can become primary CHI3L1 sources under chronic inflammatory conditions." (PMID 41488645, 2025). "Additionally, mud pack therapy and soy protein can regulate Chi3l1 levels and have potential applications in the treatment of osteoarthritis." (PMID 39769202, 2024). "This led to the identification of 411 differentially expressed genes (DEGs) related to osteoarthritis, 2485 DEGs among subgroups, as well as 238 intersecting genes and 5 hub genes (MMP13, FAM26F, CHI3L1, TAC1, and CKS2)." (PMID 40216809, 2025). "Several studies reported that levels of human cartilage glycoprotein chitinase 3-like-1 (CHI3L1) are known as a potential marker for the activation of chondrocytes and the progression of Osteoarthritis (OA), whereas lubricin appears to be chondroprotective." (PMID 26978347, 2016). "Notably, several other hub genes and genes associated with upstream regulators highlighted in our study—such as TIMP2, POSTN, and CHI3L1—are also critical regulators of ECM remodeling in other degenerative and fibrotic conditions, including osteoarthritis." (PMID 40565255, 2025).
Stroke (35 papers, 2010 to 2026). Sudden impairment of blood flow to a part of the brain due to occlusion or rupture of an artery to the brain. "Yet broad inhibition is challenging because CHI3L1 also supports homeostasis: global loss worsens stroke and promotes tumor metastasis." (PMID 41480772, 2026). "Elevated CHI3L1 levels are correlated with increased mortality and recurrence risk, suggesting that CHI3L1 is a potential biomarker for stroke severity." (PMID 39827337, 2025). "According to previous reports, Chi3l1 deficiency contributes to stroke development by enhancing neuroinflammation through decreasing STAT6-dependent M2 macrophage polarization." (PMID 39769202, 2024). "Previous studies have shown the association of the CHI3L1 gene promoter region polymorphisms with stroke, schizophrenia, personality trait, atrial fibrillation, asthma and reduced lung function." (PMID 25486056, 2014). "Recent studies revealed that CHI3L1 had an immunosuppressive function, such as, CHI3L1 negatively regulates T cell activation, and deficiency of CHI3L1 accelerates stroke development through enhancement of neuroinflammation via decreasing M2 macrophage polarisation." (PMID 33664231, 2021). "This may be relevant for CHI3L1 because previous studies have reported an exclusive association with stroke." (PMID 28319050, 2017). "Since activated NSCs and reactive astrocytes share similar transcriptional properties but have distinct morphology, we performed immunostaining of NES/KI67, NES/VIM, and NES/CHI3L1 in the stroke-injured DG." (PMID 38607670, 2024). "In mouse stroke models, KO of Chi3l1 inactivates microglial M2 polarization, enhances neuroinflammation and exacerbates ischemia-reperfusion injury 56, which is in line with our findings in mouse HIR." (PMID 37771779, 2023). "CSF samples from healthy aged controls, AD, ALS and stroke showed statistically significant elevated levels of CHI3L1 compared to young controls." (PMID 20540736, 2010). "While elevated CHI3L1 is associated with poorer outcomes, the total absence of CHI3L1 exacerbates neuroinflammation and accelerates stroke progression." (PMID 39827337, 2025). "CHI3L1 is also known to be expressed in various other neurological diseases under neuroinflammatory conditions, and the deletion of CHI3L1 was shown to accelerate strokes in mice." (PMID 36009416, 2022). "In case-control and community-based studies, elevated levels of CHI3L1 were associated with increased risk of stroke, but not MI." (PMID 28319050, 2017). "These insights into CHI3L1’s dual role in ischemic stroke suggest that therapeutic strategies aimed at modulating its activity could help balance the inflammatory responses, offering a promising direction for improving stroke management and patient recovery." (PMID 39827337, 2025). "While the GFAP and CHI3L1 levels are known to be increased in strokes, and the GFAP elevation may help differentiate intracranial haemorrhage from ischemic stroke, the correlation of the two astroglial markers with CSVD severity and other CSVD markers remains uncertain." (PMID 36009416, 2022). "CHI3L1 transcript was also found in other neurodegenerative diseases like AD, ALS and Pick's disease as well as stroke, although to a lesser extent than SIVE and MS." (PMID 20540736, 2010). "For example, in CHI3L1-KO mice with occlusion of the middle cerebral artery injury, the absence of CHI3L1 accelerates stroke development through the activation of STAT6-dependent M2 microglia." (PMID 38003338, 2023).
cognitive decline (31 papers, 2011 to 2026). "Elevated cerebrospinal fluid (CSF) levels of CHI3L1 have been linked to disease severity and cognitive decline, particularly in AD and MS, highlighting its potential for clinical diagnostics." (PMID 39827337, 2025). "Elevated levels of CHI3L1 in the CSF and brain tissues have been associated with cognitive decline in AD patients." (PMID 39827337, 2025). "Recent research utilizing positron emission tomography (PET) imaging has shown that elevated CSF CHI3L1 and GFAP levels correlate with tau and Aβ burdens, respectively, both of which are associated with cognitive decline." (PMID 39827337, 2025). "Cerebrospinal fluid (CSF) candidate markers (CHI3L1, parvalbumin) and synaptic proteins (SNAP-25, neurogranin, β-synuclein) may help identifying patients at higher risk of cognitive decline." (PMID 41960777, 2026). "CSF YKL-40 (also known as chitinase-3-like protein 1 (CHI3L1)), a glycoprotein secreted primarily by activated astrocytes, has been linked to disease progression, cognitive decline, and regional atrophy, though results vary across cohorts." (PMID 41442069, 2025). "However, CHI3L1, as well as phosphorylated tau and phosphorylated tau/Aβ and total tau/Aβ combinations, have a predictive value of cognitive decline in PD during follow-up, as revealed by correlating CSF levels with cognitive measurements." (PMID 37047273, 2023). "Hermansson and the colleagues identified increased CHI3L1 expression in the brains of HAD patients, correlating with their cognitive decline." (PMID 39827337, 2025). "The significant correlation between CHI3L1 and NPTX2 in MCI and NCI suggests an interaction between astrocytes and neurons during the early stage of cognitive decline." (PMID 32066474, 2020). "Together, these observations suggest that CHI3L1 and NPTX2 should be considered as novel biomarkers to improve the diagnosis and prediction of cognitive decline during the progression of AD." (PMID 32066474, 2020).
liver disease (27 papers, 2007 to 2025). "Chitinase-3-like protein 1 (Chi3l1) is a member of the mammalian Chitinase-like protein family, and several studies reported that Chi3l1 is associated with various inflammatory diseases as well as liver diseases." (PMID 40196357, 2025). "Serum chitinase-3-like protein 1 (CHI3L1) is a diagnostic marker for liver diseases, such as hepatocellular carcinoma (HCC)." (PMID 38304922, 2024). "In liver disease, CHI3L1 serves as a common diagnostic biomarker for hepatitis-related fibrosis." (PMID 40821115, 2025). "Additionally, CHI3L1 levels increase in portal hypertension and are associated with hepatic function." (PMID 40821115, 2025). "In this review, we comprehensively summarize the application of CHI3L1 and CHI3L1-based models as biomarkers for various liver diseases." (PMID 40821115, 2025). "This review highlights CHI3L1's dual roles as both a biomarker and regulator in various liver diseases, aiming to broaden researchers' understanding of its potential applications." (PMID 40821115, 2025). "CHI3L1 can be used as a biomarker for prognostic assessment and targeted therapy in liver diseases, which also needs to be validated by using the CLIA." (PMID 38304922, 2024). "In conclusion, we validated the CLIA for the rapid determination of serum CHI3L1 levels in HBV-related liver diseases." (PMID 38304922, 2024). "CHI3L1 and macrophage polarization certainly play an important role in the progression of liver diseases, making it particularly important to study the physiological function of CHI3L1 in liver diseases." (PMID 38003338, 2023). "Elevated serum levels of Chi3l1 have been observed in various liver diseases, such as hepatic fibrosis, non-alcoholic fatty liver, alcoholic liver disease, and hepatocellular carcinoma." (PMID 34110284, 2021). "The elevation of serum levels of Chi3l1 has been observed in various liver diseases, but studies of its involvement in liver diseases have only begun to emerge." (PMID 34110284, 2021). "In summary, we found that serum CHI3L1 has stage expression feature in different stage liver disease with chronic HBV infection." (PMID 31916309, 2020). "Additionally, we explore the CHI3L1-mediated pathways in liver disease pathology, aiming to enhance researchers' understanding of CHI3L1 as biomarkers and therapeutic targets." (PMID 40821115, 2025). "Moreover, the “Guidelines on the Prevention and Treatment in Chronic Hepatitis B” emphasized the predictive role of CHI3L1 in HBV-related liver diseases." (PMID 38304922, 2024). "In clinical applications, studies have shown that CHI3L1 levels were significantly elevated in liver diseases and increased with the severity of the disease, which was also emphasized in the “Guidelines on the Management of Hepatic Encephalopathy in Cirrhosis”." (PMID 38304922, 2024). "In summary, we demonstrated that CHI3L1 is a novel secreted factor that mediates the immunosuppressive effects of hUC-MSCs and provided new insights into promising therapeutics for refractory liver diseases." (PMID 33664231, 2021). "Monoclonal antibodies targeting Chi3L1 protein function may significantly improve insulin sensitivity and decrease lipid accumulation and may alter the progression of this serious liver disease." (PMID 33498326, 2021). "Furthermore, serum CHI3L1 has been recommended as a noninvasive marker for liver diseases." (PMID 38304922, 2024). "The decrease in CHI3L1 levels in the treated group may therefore be related to a reduction in inflammatory processes associated with schistosome infection and egg laying, and support previous studies in liver disease that suggests CHI3L1 levels are a bio-indicator of early phases of fibrogenesis." (PMID 23145202, 2012). "Herein, we aimed to evaluate the analytical performance of a chemiluminescent immunoassay (CLIA) for the quantitative detection of CHI3L1 and its application in hepatitis B virus (HBV)-related liver diseases." (PMID 38304922, 2024).
liver disease (continued). "Considering the important clinical value of CHI3L1, we evaluated the CLIA for serum CHI3L1 detection in HBV-related liver diseases." (PMID 38304922, 2024). "In this study, we evaluated the analytical performance of a CLIA to quantitatively detect CHI3L1 and the value of CHI3L1 in diagnosing HBV-related liver diseases." (PMID 38304922, 2024). "Chitinase-3-like protein 1 (CHI3L1), an inflammatory response factor that participates in various biological processes and is abundant in liver tissue, holds promise as a potential biomarker for liver diseases." (PMID 38962736, 2024). "The specific physiological effects of CHI3L1 in various liver diseases have not been thoroughly studied." (PMID 38003338, 2023). "In advanced liver disease, the inflammatory factor TNF-α exerts a pro-carcinogenic effect through CHI3L1, leading to the accumulation of lipid peroxide, whereas in MAFLD, CHI3L1 induces an increase in lipid content in hepatocytes through the AKT, glycogen synthase kinase (GSK), and ERK pathways." (PMID 39068486, 2024). "However, the biological function of Chi3l1 in liver disease is not clear." (PMID 34110284, 2021).
COVID-19 (26 papers, 2021 to 2026). A disease caused by infection with severe acute respiratory syndrome coronavirus 2. "In COVID-19, CHI3L1 is reported to be associated with severe disease, although it is not correlated with mortality." (PMID 36331721, 2023). "Studies from our laboratory and others have also demonstrated that the levels of circulating CHI3L1 are also increased in the diseases that are COVID-19 risk factors." (PMID 34747367, 2021). "Also, we are not able to totally exclude the underlying effect of other undetected conditions such as immunosuppression, CHI3L1 gene variants, and COVID-19 status." (PMID 36880855, 2023). "In spite of the important differences in the S proteins of the variants and the impressive importance of S and ACE2 in COVID-19, therapies that focus on host targets such as CHI3L1, ACE2, and SPP that are effective in multiple SC2 variants have not been adequately defined." (PMID 35735790, 2022). "We hypothesized that therapies that target the host factors involved in SC2 infection like CHI3L1 can contribute to the control of COVID-19 induced by all viral variants that use ACE2." (PMID 35735790, 2022). "In addition, studies from our laboratory and others have demonstrated that the levels of circulating CHI3L1 are also increased in the very diseases that are COVID-19 risk factors, where they correlate with disease severity." (PMID 34747367, 2021). "Therefore, higher levels of CHI3L1 might be associated with the pathogenesis of COVID-19, especially in terms of pulmonary tissue damage and repair." (PMID 34667241, 2021). "The protein-protein interaction network analysis identified CHI3L1 as a key gene linking PD and COVID-19." (PMID 41930954, 2026). "A recent study showed that CHI3L1 was significantly correlated with severe state and adverse prognosis for COVID-19 patients." (PMID 36092895, 2022). "Further studies are warranted to identify the stimulus involved in the persistent generation of CHI3L1 in patients with COVID-19 and the reasons of its preferential early accumulation in patients who will experience adverse outcomes." (PMID 35534648, 2022). "We found that plasma levels of CHI3L1 were reduced in COVID-19 survivors four weeks after clinical remission, at a time when systemic inflammation had returned to baseline levels." (PMID 35534648, 2022). "We found that serum CHI3L1 levels were elevated in COVID-19 patients with severe disease and adverse prognosis." (PMID 34667241, 2021). "Human studies also demonstrate that the levels of circulating CHI3L1 are increased in the elderly and patients with CM, where they correlate with COVID-19 severity." (PMID 34747367, 2021). "CHI3L1 plays a critical role in the pathogenesis of and is an attractive therapeutic target in COVID-19." (PMID 34747367, 2021). "Lastly, human studies demonstrated that the levels of circulating CHI3L1 are increased in COVID-19+ patients who are elderly, have comorbid diseases, and manifest severe COVID-19 disease." (PMID 34747367, 2021). "ScRNA-seq analysis revealed a significant increase in CHI3L1-expressing astrocytes in COVID-19 samples, indicating a potential mechanism by which COVID-19 may exacerbate PD symptoms." (PMID 41930954, 2026). "Also, olivary hilar astrocytes increased YKL-40 (CHI3L1) in COVID-19, but to a lesser extent than ARDS astrocytes." (PMID 37483351, 2023). "Moreover, further research has found that CHI3L1 enhances SC2 infection by using the CHI3L1 axis, playing a critical role in the pathogenesis of COVID-19, and is an attractive therapeutic target." (PMID 38003338, 2023). "And anti-CHI3L1 inhibitors and Kanamycin partially inhibit the infection of epithelial cells by these variant-of-concern (VOC) pseudo-viruses, once again proving that CHI3L1 is a common and VOC-independent therapeutic target in COVID-19." (PMID 38003338, 2023). "Plasma CHI3L1 is increased in COVID-19 patients and predicts adverse outcome." (PMID 35534648, 2022).